OR8G2P (olfactory receptor family 8 subfamily G member 2 pseudogene)
Description:
Odorant receptor.
Synonyms: OR8G2; OR8G4; TPCR120; HSTPCR120; ORL206; ORL486
Gene: Protein-coding gene on chromosome 11 (124,224,732 to 124,225,666, forward strand). Ensembl gene ENSG00000181214.
Subcellular location: Cell membrane
Genetic constraint (gnomAD): Missense variants: 312 observed, 352.45 expected, observed/expected ratio (o/e) 0.89, 90% interval 0.81 to 0.97. Synonymous variants: 109 observed, 134.52 expected, observed/expected ratio (o/e) 0.81, 90% interval 0.69 to 0.95.
Homologues: Orthologues: chimpanzee OR8G2P (89% identical), dog OR8G3 (79% identical), mouse Or8g2 (79% identical), mouse Or8g2b (75% identical), rat Or8g2c (75% identical), tropical clawed frog or5dd2b (41% identical). Paralogues in human: OR8G3 (87% identical), OR8G1 (74% identical), OR8G5 (72% identical), OR8A1 (63% identical), OR8B3 (61% identical), OR8B2 (60% identical), OR8D2 (59% identical), OR8D1 (58% identical), OR8B8 (58% identical), OR8D4 (57% identical), OR8B4 (56% identical), OR8B12 (56% identical), and 84 more.